IL1B (interleukin 1 beta)
Diseases named in the same sentence as IL1B in open-access papers (continued):
Sharing a sentence is not in itself a finding about the gene and the disease.
COVID-19 (continued). "Interactions between the five genes shared by all the investigated metals and COVID-19 (CXCL8, IL1B, IL10, IL6, and TNF) are mainly physical, whereas the dominant interaction between the genes affected by individual metals is co-expression." (PMID 38963144, 2024). "The relationship between the expression of miR-9, the transcription factor NF-κB, and the pro-inflammatory cytokines IL-6, IL-1β, and TNF-α in a cohort of COVID-19 patients was investigated." (PMID 39201618, 2024). "In contrast, after vaccination against COVID-19, a lower TNF-α and IL-1β production capacity was observed, complemented by higher anti-inflammatory IL-1Ra production capacity." (PMID 39744634, 2024). "IL-6, a pro-inflammatory cytokine that can be induced by IL-1β and a significant inducer of CRP, is consistently elevated in the serum of COVID-19 patients and strongly predicts poor prognosis." (PMID 39452786, 2024). "The increased expression of pro-inflammatory cytokines IL-6, IL-1β, and TNF-α in COVID-19 patients compared to the control group confirms the sequence of events following NF-κB activation." (PMID 39201618, 2024). "EGCG also can block the activation of NF-κB to controls the expression of many pro-inflammatory cytokines, including IL-1β, TNF-α, IL8, IL-6, all of which are induced in COVID-19." (PMID 38632501, 2024). "GMCSF, IL-13, IL-1β, IL-2, IL-4, and IL-5 were undetectable in the vast majority of both TTP and COVID-19 samples." (PMID 39337495, 2024). "Longitudinal serum cytokine analysis of 207 COVID-19 patients revealed that in early inflammatory responses, IL-6, TNF-α, IL-10, and IL-1β expression increased in those with severe disease." (PMID 38710800, 2024). "Transcriptomic studies of COVID-19 patients revealed upregulated cytokine (TNF, CXCL8, IL1B, IL6, IL10, IL12) and chemokine (CCL2, CCL3, CCL4, CCL20, CXCL2, CXCL9, CXCL10) expression in monocytes as one major dysregulation in these patients." (PMID 38391913, 2024). "The levels of cytokines, including IL-6, IL-1β, IL-10, IFN-γ, tumor necrosisfactor-α (TNF-α), and colony-stimulating factor (CSF), gradually increase with theseverity of COVID-19 and play a crucial role in the immune response to SARS-CoV-2 infection." (PMID 39759510, 2024). "In patients with severe COVID-19, a cytokine storm is often triggered, characterized by an excessive release of pro-inflammatory cytokines such as IL-6, TNF-α, and IL-1β." (PMID 39720706, 2024). "The log2 fold change of differentially expressed genes (DEGs) in monocytes within PBMCs of severe and mild COVID-19 patients confirmed the log2 fold change observed in NLRP3 (0.22), CASP-1 (0.29) and IL-1β (1.16) during severe stages of SARS-CoV-2 infection." (PMID 38748756, 2024). "OAS1 gene, an interferon stimulated gene (ISG), showed significant upregulation by IFN-I in COVID-19 PMNs as compared to HC PMNs, while the inflammasome related genes IL-1β, CASP1 and NLRC5 were more efficiently induced in HC PMNs than COVID-19 PMNs." (PMID 39172744, 2024). "Previous studies found a positive correlation between increased serum levels of IL-1β, IL-18, and LDH in COVID-19 patients and the severity of the disease, suggesting the involvement of inflammasomes in the pathogenesis of SARS-CoV-2." (PMID 38399989, 2024). "Specifically, IL-1β, TNF-α and IL-6, all of which are elevated in COVID-19, are potent activators of the p38 MAPK signalling cascade, which itself leads to further production of these cytokines." (PMID 39051370, 2024). "The RNAseq data on whole blood (EGAS00001004503) of 10 controls, 20 severe and 19 mild COVID-19 patients showed log2 fold change in NLRP3 (1.25), CASP-1 (1.21) and IL-1β (1.38) in severely infected patients only." (PMID 38748756, 2024). "In our study, a significant increase in IL-1β and TNF-α serum levels was exclusively observed in carriers of the TT genotype of the rs2070788 TMPRSS2 SNP in COVID-19 patients compared to healthy controls." (PMID 39188881, 2024).
COVID-19 (continued). "IL1B, a proinflammatory cytokine, has been found to increase in the bronchoalveolar lavage (BAL) fluid of COVID-19 patients compared to healthy controls." (PMID 39590591, 2024). "The NF-κB transcription factor is activated by cytokines such as IL-1β, IL-6 and TNF-α, which are elevated in severe COVID-19." (PMID 39051370, 2024). "The cytokine profile of COVID-19 is characterized by elevated levels of pro-inflammatory cytokines, such as IL-6, TNF-α, IL-1β, and IFN-γ." (PMID 39130641, 2024). "An in-depth understanding of the exact role and regulatory mechanism of IL-18 and IL-1β in SARS-CoV-2 infection is very important for the formulation of targeted treatment strategies and the effective management of COVID-19." (PMID 38399989, 2024). "Multiple proinflammatory cytokines were found elevated in the sera of COVID-10 patients, among which are IL-1β, IL-6, and TNF-α, which correlated with COVID-19 severity and mortality." (PMID 38183501, 2024). "Based on relevant results reported in the existing literature and a previous study of our group, the genes CCL5, OAS1, IRF9, IFI6, TGFB1, IL1B, and TFRC were analyzed in the present study in relation to the severity of COVID-19." (PMID 38731851, 2024). "The findings from this investigation unveiled heightened plasma levels of key proinflammatory cytokines, including interleukin IL-1β, IL-6, TNF-α, monocyte chemoattractant protein-1, and soluble intercellular adhesion molecule-1 in COVID-19 patients." (PMID 38448675, 2024). "In a Syrian hamster model with SARS-CoV-2 GFP/ΔN, the HSP90 inhibitor 17-DMAG significantly reduced COVID-19 lung injury and gene expression of TNF, IL1B and IL6, but clinical deterioration was observed (weight loss exceeding 20% body weight and ruffled fur)." (PMID 39325762, 2024). "In the present study, the differential expression of seven genes related to immunity, IRF9, CCL5, IFI6, TGFB1, IL1B, OAS1, and TFRC, was analyzed in individuals with COVID-19 diagnoses of different disease severities." (PMID 38731851, 2024). "As patients recuperate from COVID-19, cytokine levels including TNF-α, TGF-b, IFN-g, IL-1b, IL-2, and IL-4 subside." (PMID 38844850, 2024). "We found that COVID-19 patients with the 4G4G genotype had high PAI-1 transcript levels in PBMCs and low circulating plasmin and IL-1β or proTGFβ levels, indicating a mild inflammatory response." (PMID 39281671, 2024). "Among these genes, CD1C, IL1B, and SLP1 have emerged as key IRGs with potential protective effects against COVID-19." (PMID 39622956, 2024). "In mild-moderate COVID-19, the cytokine storm is similar to that observed in typical ALI and ARDS, with increased levels of proinflammatory cytokines such as IL-1β, IL-6, and TNF-α." (PMID 39130641, 2024). "Therefore, inhibition of the NLRP3 inflammasome could potentially lead to a corresponding decrease in the levels of strongly pro-inflammatory cytokines, especially IL-1β, which is released from pyroptotic macrophages and monocytes in large amounts in COVID-19 ARDS." (PMID 39051370, 2024). "High levels of these molecules, detected after macrophage treatment with VLPs (TNFα, IL-1β, CCL8, CXCL8, CXCL9, CXCL16, CXCL1, and CXCL2), were shown to correlate with severe COVID-19 in other studies." (PMID 38664730, 2024). "In contrast to IL-1β, IL-1Ra and IL-6 are generally secreted at higher concentrations and appeared elevated in both BALF and serum of COVID-19 patients." (PMID 39882243, 2024). "This protein mediates the secretion of IL-1β, requiring K+ outflow and mitochondrial ROS production, elucidating the potential of the NLRP3 inflammasome as a molecular target for COVID-19 treatment." (PMID 38399989, 2024). "Lung tissues, peripheral blood mononuclear cells and monocytes of severe COVID-19 patients displayed increased NLRP3 activation and increased levels of IL-1β." (PMID 38748756, 2024).
COVID-19 (continued). "In order to test the potential impact of RIC in the setting of COVID-19, we selected a panel of pro-inflammatory cytokines that included IL-6, TNF-α, IL-1β, and IFN-γ." (PMID 36445625, 2024). "A comparative analysis of cytokines in BALF and blood plasma of severe patients with ARDS against the background of COVID-19 showed increases in the levels of TNF-α, IL-1α, IL-1β, IL-1ra, IL-6, IL-10, and IL-33 cytokines relative to healthy donors." (PMID 39457048, 2024). "In a double-blind, randomised, placebo-controlled trial involving adults recently diagnosed with COVID-19, four weeks of PEA supplementation led to significant reductions in IL-1β and IL-2 concentrations." (PMID 39062193, 2024). "During COVID-19, strong activation of the NLRP3-inflammasome and caspase-1 is induced with subsequent release of IL-1β and IL-18, although these cytokines remain difficult to detect in patient’s blood." (PMID 39882243, 2024). "Severe manifestations of COVID-19 may be partly accounted for by an autoimmune reaction mediated by a dysregulated network of circulating proinflammatory cytokines and inflammatory markers, including IL-1β, IL-6, IL-2, IL-8, IL-17, TNF-α, C-reactive protein, D-dimer, and antibodies." (PMID 37712090, 2023). "In severe COVID-19 cases, IFN-I response arouses an excessive inflammatory response by promoting TNF/IL-1β-driven inflammation leading to cytokine storm." (PMID 36949448, 2023). "The marked increase in COVID-19 disease severity is a result of neutrophil migration and G-CSF, TNF-a, IL-1b and IL-6 activation." (PMID 37091818, 2023). "In patients with COVID-19, NLRP3 inflammasome activation and its dependent caspase-1 and GSDMD cleavage as well as subsequently IL-1β secretion have been demonstrated, suggesting that NLRs and inflammasome sensors are involved in SARS-CoV-2 infection as well." (PMID 36776881, 2023). "Patients with mild/moderate illness showed significantly higher expression levels of IL-6, IL-1β, IL-10, CRP and IDO1 than COVID-19-free subjects." (PMID 37715121, 2023). "Another interesting finding was the increased serum levels of IL-1β, IL-3, IL-17, and CCL3 in severe COVID-19 exclusively." (PMID 37373331, 2023). "Indeed, studies of patients with COVID-19 have reported the increment of inflammatory monocytes and neutrophils, a sharp decrease in lymphocytes, and an inflammatory milieu containing interleukin (IL)-1β, IL-6, and tumor necrosis factor (TNF) in severe disease." (PMID 36703213, 2023). "In co-infected patients:↑ TNF-α, MIP-1β, and IL-9 compared with COVID-19-only.↑ TNF-α, IL-1β, IL-17A, IL-5, FGF-basic, and GM-CSFcompared with TB-only.↓ specific response to SARS-CoV-2 and Mtb." (PMID 37662901, 2023). "For example, elevated levels of IL-1β, Casp1p20, IL-1RA, IL-18, and lactate dehydrogenase (LDH) were detected in severe COVID-19 patients’ plasma." (PMID 37508374, 2023). "Referring to blood cytokines, in COVID-19 patients there is a significant reduction in TNF (p < 0.0001) and IL-1β levels (p < 0.0001)." (PMID 36861136, 2023). "Consistent with our findings in TB patients, prior COVID-19 led to reduced levels of IFN-γ, IL-1β, IL-7 and TNF-α in ORD patients." (PMID 38179046, 2023). "More specifically, and according to our models, dexamethasone is able to modulate COVID-19 evoked ARDS through pathways with wide effects in inflammation, such as those activated by NF-κB, IL-1β and TNFα." (PMID 36791125, 2023). "Severe pulmonary disease symptoms of COVID-19, which are a consequence of tissue damage due to an exacerbated inflammatory response, are marked by elevated levels of TNF-α, IL-1β, and other inflammatory mediators." (PMID 37854602, 2023). "Overall, higher IL-1β, IL-6, and TNF- α levels were reported in COVID-19-infected patients compared to patients with periodontitis." (PMID 37106750, 2023). "Taken together, these data indicate that IL-1β, caspase-1, ASC and IL-18 are reliable biomarkers of COVID-19." (PMID 37168848, 2023).
COVID-19 (continued). "Of the analyzed pro-inflammatory cytokines, the concentrations of interleukin (IL)-1β, monocyte chemotactic protein 1 (MCP-1), IL-6, IL-8 and IL-17A were significantly higher in severe COVID-19 patients compared to healthy controls." (PMID 36851312, 2023). "In this study, we first found that the gene expression of NLRP3 and IL-1β was downregulated in the CD14+ and CD16+ monocytes from COVID-19 patients, while MARCH7 and IL-18 declined only in the CD16+ monocytes." (PMID 38004809, 2023). "IL-1α, IL-1β, IL-8, IFN-γ, VEGF-A, and TNF-α had returned to normal levels 6 months after recovery, but IL-1Rα was still elevated in COVID-19 convalescents, compared to healthy controls." (PMID 37077911, 2023). "The mediators IL-1β, IL-6, IL-10, TNF-α, IL-8/CXCL8, IL-1RA, IL-18/IGIF, and sTNFR1 were all increased in patients with COVID-19 and followed the rate of elevation as clinical worsening progressed." (PMID 36851766, 2023). "In COVID-19, patients with confirmed bacterial infections, blood level of neutrophils, CRP, ferritin, IL-1β, IL-2R, IL-6, and TNF-α were higher than the upper limits of the normal values with significant differences, while lymphocyte was significantly lower." (PMID 37771749, 2023). "Dexamethasone, by targeting the glucocorticoid receptor is able to modulate COVID-19-evoked ARDS through pathways with wide effects on inflammatory factors, such as NF-κB, IL-1β, TNFα and IL-6, as well as fibrosis." (PMID 36791125, 2023). "In contrast, IL1B and IL18 transcripts were expressed in the SPP1/MERTK+ (inflammatory monocyte-derived) macrophage cluster in the COVID-19-infected samples." (PMID 37737611, 2023). "Anakinra is an antagonist of IL‐1 receptor, which inhibits IL‐1α and IL‐1β activities, and is approved by the FDA to be used to treat adult COVID-19 inpatients with positiveness of COVID-19 with pneumonia and requiring supplemental oxygen." (PMID 37726282, 2023). "In addition, we showed that the cytokines IFN-γ, IL-2, IP-10, IL-1β, IL-6, IL-8, and TNF could discriminate the status of SARS-CoV-2 infection or exposition, and also it highlighted the high levels of pro-inflammatory IL-1β and IL-6 in long-COVID-19 when compared to the unexposed group." (PMID 37018291, 2023). "The expression levels of NLRP3, NLRP6, IL-1β, and MARCH7 were decreased in COVID-19 patients, and this reflected the inhibition of the NLRP3 inflammasome pathway." (PMID 38004809, 2023). "As in previous studies, we found increased serum levels of IP-10, IL-1β, IL-6, and IFN-λ2/-3 in patients with MIS-C and in patients with severe COVID-19 compared with controls." (PMID 36282598, 2023). "It was reported that COVID-19 patients exhibited high plasma levels of C-C motif chemokine ligand 2 (CCL2), CXCL10, IFN-γ, IL-1β, IL-7, IL-8, IL-10 and TNF-α." (PMID 37251383, 2023). "Along with the upregulation of inflammatory mediators such as IL1B, TNF, and IL6, the downregulation of CCL5 can be a major contributor to COVID-19-mediated neuroinflammation." (PMID 37686360, 2023). "The levels of many proinflammatory cytokines (IL-1β, IL-6, IL-8, IL-17, TNF, G-CSF, GM-CSF) and chemokines (IP10, MCP1, MIP1α), were elevated in COVID-19 patients, with higher levels in critically ill subjects." (PMID 36672688, 2023). "High levels of IL-1β, IL-18 and LDH positively correlate with disease severity in COVID-19 patients, suggesting that inflammasomes participate in SARS-CoV-2 pathogenesis." (PMID 37920468, 2023). "In the subset analysis, which included serum samples from COVID-19 positive women during the acute phase of illness, significant heterogeneity was also observed for most cytokines, except for IFN-γ, IL-1β, and IL-17." (PMID 37915987, 2023). "Our data reveals that IL-1β level was significantly increase in the COVID-19 positive patients, and this level significantly increases in ICU admitted patients; this makes IL-1β a good predictor of the disease severity and patient’s outcome." (PMID 37222789, 2023).
COVID-19 (continued). "Transcriptome profiling of in vitro models of the airway epithelium revealed increased expressions of IL-1β, TNF-α, CCL2, CCL20, CCL8, CXCL2, CXCL8, and CXCL16 (all of which are upregulated in severe COVID-19), resulting in lung injury and multiorgan failure." (PMID 37631998, 2023). "Previous work has shown that IL1B, IL18, and CXCL10 are induced by SARS-CoV-2 infection and contribute to COVID-19 pathogenesis." (PMID 37737611, 2023). "Few studies in the Eastern Mediterranean Region reported higher serum levels of IL-1β, IL-6, IL-8, and TNF in severe COVID-19 patients compared to mild cases." (PMID 37228441, 2023). "Early reports of COVID-19 showed elevated levels of pro-inflammatory cytokines, e.g., IL1b, TNF and IL6, especially among severe COVID-19 cases, implicating a cytokine-storm process." (PMID 36829233, 2023). "Incubation of platelets from COVID-19 patients with monocytes from healthy donors triggers the release of IL-1β, IL-6, IL-8, MIP-1α, MCP-1, TNF-α, PF4, and PDGF, and elevated levels of these factors were observed in clinical samples from COVID-19 patients." (PMID 38069209, 2023). "The data shows that cytokines like IL-6, TNF-a, and IL-1β are produced by both the influenza virus and SARS-CoV-2, though levels are higher in COVID-19 patients." (PMID 37200377, 2023). "Through stimulation with the recombinant SARS-CoV-2 S protein in whole blood, we identified a signature for COVID-19 based on the cytokines IFN-γ, IL-2, IP-10, IL-1β, IL-6, IL-8, and TNF." (PMID 37018291, 2023). "IL-1β secretion is reduced when SARS-CoV-2 was preincubated and neutralized with COVID-19 patient’s serum before infection of ACE2-A549 cells, thus revealing that NLRP3 inflammasome is activated after viral entry into permissive host cells." (PMID 37920468, 2023). "This means that the body avoids a prolonged inflammatory response and its damaging effects since it is known that there is increased expression of pro-inflammatory cytokines IL–1β, IL–6, TNF, IL–12, IFN–β, IFN–γ, IL–17 in COVID-19." (PMID 36833234, 2023). "Our results showed significantly higher level of IL-1β, TNF-α, IL-12 and IL-10 in patients with stage IV of COVID-19 in comparison to milder forms of the disease." (PMID 36702907, 2023). "We also examined the expression of previously reported inflammatory cytokines (TNF, IL6, IL1B, CCL3, CCL4 or CXCL2) produced by circulating monocytes in patients with COVID-19." (PMID 37363730, 2023). "They identified drugs targeting IL-1β, IL6, IL-6Rα, and TNF-α, as well as corticosteroids, through interactome mapping between COVID-19-related proteins and their known drug targets according to current therapeutic approaches." (PMID 37631998, 2023). "Overproduction of cytokines, including IL-17, IL-7, IL-1β, IL-9, IL-2, IL-10, TNF-α, GM-CSF, G-CSF, IFN-γ, MCP1, MIP1A, MIP1B, CXCL10 and CXCL8, by monocytes and macrophages has been reported in severe COVID-19 cases." (PMID 36793739, 2023). "Clinical studies have shown abnormal concentrations of different relevant cytokines in patients with COVID-19, such as IL-6, TNF-α, IL-1β." (PMID 38018195, 2023). "Much evidence showed that there are many similar inflammatory pathways between periodontitis and COVID-19, such as NF-κB pathway, NLRP3/IL-1β pathway, and IL-6 signaling pathway." (PMID 36769328, 2023). "Among these cytokines, levels of IL-1β, IL-6 and TNF-α were also significantly elevated in individuals with ongoing post-acute sequelae of COVID-19, and they were positively correlated with each other." (PMID 37674675, 2023). "Clinical studies have shown that adjuvant therapy with quercetin in early COVID-19 patients significantly reduced the release of proinflammatory factors, such as TNF-β and IL-1β, and alleviated inflammation in patients with COVID-19." (PMID 36985705, 2023).